INS (insulin)
Diseases named in the same sentence as INS in open-access papers (continued):
Sharing a sentence is not in itself a finding about the gene and the disease.
Obesity (continued). "Biomarkers, such as ferritin, leptin, resistin, interleukin-6 (IL-6), insulin, tumor necrosis factor-alpha and plasminogen activator inhibitor-1 (PAI-1), play crucial roles in the pathophysiology of obesity." (PMID 41011232, 2025). "Decreased mitochondrial respiration has been observed in the VAT of patients with obesity and MASLD, and it has been correlated with impaired insulin sensitivity." (PMID 40211057, 2025). "AT mitochondrial dysfunction correlates strongly with obesity progression and T2DM development, significantly affecting adipocyte differentiation capacity, cellular lipid metabolism, and insulin signaling responses." (PMID 40630101, 2025). "(In a rodent-based model of obesity, a reduction in IMCL content resulted in an improvement in insulin sensitivity within the SM)." (PMID 39997710, 2025). "Chronic hyperinsulinemia, as observed in T2DM and obesity, downregulates insulin receptor expression at the blood–brain barrier (BBB), limiting insulin transport into the central nervous system and exacerbating cerebral hypoinsulinemia." (PMID 41294899, 2025). "For example, several meta-analyses have demonstrated a reduced incidence of obesity-related cancers, including colorectal and prostate cancers, among patients using GLP-1RAs compared to those on insulin therapy." (PMID 40282969, 2025). "Oxidative stress, primarily driven by the overproduction of reactive oxygen species (ROS), plays a pivotal role in the pathogenesis of obesity and T2DM by impairing insulin signaling and inducing β-cell dysfunction." (PMID 40004938, 2025). "Across the SCI subgroups, men with SCI (overall group, paraplegia, tetraplegia, complete, and high sympathetic injuries) and individuals with motor-complete SCI (men and women) met CMS criteria based on obesity, low HDL-C, and insulin resistance." (PMID 40363903, 2025). "These include older hypotheses such as insulin-insulin-like growth factor, inflammatory mediators and adipokines, and sex hormones, as well as more novel hypotheses like alterations in the colonic microbiota of individuals with obesity and systematic ectopic fat (central obesity)." (PMID 39562688, 2025). "Elevated insulin and insulin-like growth factor (IGF) levels in individuals with obesity further promote cellular proliferation and inhibit apoptosis, increasing tumorigenesis risk." (PMID 40444236, 2025). "We also evaluated obesity‐related metabolic parameters after 14 weeks of HFD feeding and revealed that the blood glucose and fasting serum insulin levels were significantly lower in AAV‐oe‐βFaar mice than in control mice." (PMID 40548473, 2025). "Here, we demonstrate that in insulin resistant women, ABHD6 mRNA expression is elevated in visceral fat and positively correlates with obesity and metabolic dysregulation." (PMID 40886915, 2025). "As key metabolic regulators, SCFAs influence adipose tissue metabolism, lipid oxidation, β-cell function, and insulin secretion, suggesting a microbiota-SCFA-metabolism relationship and their potential as therapeutic targets for obesity and related diseases." (PMID 41305576, 2025). "Patients with overweight/obesity were more likely to be men, had a longer disease duration, higher values of waist circumference, triglycerides, LSM, daily insulin dose, as well as lower plasma HDL cholesterol compared with those with normal body weight." (PMID 40083078, 2025). "In experimental models of dietary obesity, chelation with DFP and DFO has been shown to reduce IL-1β expression, normalize insulin signaling, and reduce macrophage infiltration into adipose tissue." (PMID 40943225, 2025). "We found evidence suggesting a mediating role of SHBG, fasting insulin, bioavailable testosterone, and IGFBP-1 in the effects of ASAT on obesity-related cancers." (PMID 40987470, 2025). "Individuals with obesity have an accumulation of IDL in the adipose and liver, contributing to insulin signaling disruption." (PMID 40985048, 2025).
Obesity (continued). "Also, the increased circulating lipoproteins in obesity stimulate TLR2, causing adipocytes and macrophages to secrete less adiponectin and to produce pro-inflammatory cytokines, predisposing to leptin resistance in the central nervous system and insulin resistance peripherally." (PMID 39837875, 2025). "Firstly, a biased screening approach was taken where the metabolic pathways related to obesity were selected (FoxO, mTOR, cAMP, PI3K-Akt, insulin, adipocytokine, and Toll-like receptor)." (PMID 40981068, 2025). "Consistent with previous research, individuals with obesity in our study exhibited significantly higher levels of CRP, insulin, and triglycerides, all of which are established markers of metabolic dysfunction and inflammation." (PMID 41374089, 2025). "Further, continued obesity for long-term periods after parturition can exacerbate the problem of high leptin and NEFA levels, which can further impair the actions of insulin, as well as the metabolism of amino acids, lipids, and glucose in mothers." (PMID 41463818, 2025). "Specifically, ewes assigned to obesity management treatments exhibited improvements in concentrations of leptin, NEFA, insulin, and urea in plasma, as well as glucose metabolism, in comparison to the obese ewes on both PPD1 and PPD150." (PMID 41463818, 2025). "Individuals with obesity exhibited lower ghrelin, GIP, and resistin, but higher C-peptide, insulin, and leptin compared to controls." (PMID 41155711, 2025). "Orphan receptor GPRC5B maintains mature β-cell function in obesity via cAMP/CREB-dependent MafA regulation; β-cell-specific GPRC5B-knockout mice have reduced insulin secretion and develop a prediabetic condition." (PMID 40906536, 2025). "Under normal physiological conditions, insulin readily crosses the blood–brain barrier (BBB) via receptor-mediated transport, and this transport rate can be modulated by factors such as obesity, inflammation, and AD." (PMID 39966707, 2025). "Studies indicate that cinnamon supplementation may improve insulin sensitivity by enhancing glucose transporter activity and reducing oxidative stress, while also improving lipid profiles and inflammatory markers, making it a promising adjunct to obesity management." (PMID 40970779, 2025). "Similarly, a study in older Dutch adults (age ≥55 years) with obesity and T2D reported that the addition of a leucine-enriched whey protein supplement to a hypocaloric diet (600 kcal below estimated energy needs) plus exercise for 13 weeks resulted in improvements in fasting plasma insulin and IR." (PMID 40647209, 2025). "Similar findings were reported in mouse models, where diet-induced obesity (DIO) leads to an increase in β-cell area and insulin-positive cells." (PMID 41282294, 2025). "A 23-year-old female with T1D for 12 years, managed with a t: slim insulin pump and Dexcom CGM, who also had obesity (weight 93 kg, 205 lbs., BMI 30.3 kg/m2), weight 93 kg, 205 lbs." (PMID 39707844, 2025). "Chronic inflammation in obesity is mechanistically driven by dysregulated activation of inflammatory signaling pathways, particularly JNK and NF-κB, which orchestrate systemic insulin resistance through interconnected molecular mechanisms." (PMID 40699756, 2025). "We demonstrated that, collectively, men with SCI (overall group, paraplegia, tetraplegia, complete, and high sympathetic injuries) and individuals with motor-complete SCI (men and women) met CMS criteria based on obesity, low HDL-C, and insulin resistance." (PMID 40363903, 2025). "Different evidence suggests that obesity contributes to CKD through mechanisms that involve chronic inflammation, hemodynamic alterations, insulin resistance, and lipid accumulation." (PMID 41009007, 2025). "In the Look AHEAD study, participants with overweight, obesity, and T2DM, with BMI > 25 kg/m2 or > 27 kg/m2 if receiving insulin and an age range of 45–76, were randomized to lifestyle intervention (ILI) or diabetes support and education." (PMID 41062431, 2025).
Obesity (continued). "Mitochondrial oxidative capacity plays a central role in the onset and progression of obesity and NAFLD and is influenced by factors such as body mass, age, insulin sensitivity, coexisting T2DM, chronic alcohol intake, and possibly genetic variants." (PMID 41462693, 2025). "This is consistent with previous reports showing that GLP-1 levels and secretion increased during obesity development protected against glucose intolerance induction, and GLP-1 treatment improved insulin sensitivity in rodents fed an HFD." (PMID 40690443, 2025). "Significantly, PIK3AP1, encoding an adaptor in the PI3 K signaling pathway, differentially expressed in both fat depots, correlated strongly with obesity-related traits such as HOMA-IR, fasting insulin, glucose, and triglyceride levels." (PMID 40862085, 2025). "Obesity results in lower concentrations of GLP-1, PYY, and ghrelin, whereas insulin and glucagon are increased." (PMID 41043686, 2025). "Children with obesity had lower HDL and DHEA and higher triglycerides, glucose, insulin concentration, and HOMA-IR than the control group." (PMID 39931045, 2025). "CMDs, such as obesity, T2D, or MASLD, encompass a cluster of processes that impair insulin sensitivity, glucose and lipid metabolism, and immune function." (PMID 40006091, 2025). "Adipose tissue dysfunction in obesity triggers the release of pro-inflammatory cytokines (e.g., TNF-α, IL-6) and reduces adiponectin, an anti-inflammatory and insulin-sensitizing adipokine." (PMID 40181314, 2025). "Increasing evidence suggests that the pathophysiology of obesity involves neuroinflammation, hypothalamic dysfunction, and significant endocrine dysfunction, including the regulation of leptin (LEP), ghrelin, insulin, and reproductive hormones." (PMID 41226484, 2025). "Individuals with obesity showed significantly elevated CS markers, along with reduced expression of GLUT4 and PAX7, indicating impaired insulin action and regenerative potential." (PMID 40127780, 2025). "Previous studies have noted that increased plasma amino acid concentrations are most commonly observed in individuals with obesity and SLD, possibly due to heightened insulin resistance and protein catabolism." (PMID 39877862, 2025). "Although insulin signaling in MCH neurons appears dispensable under normal physiological conditions, it becomes functionally significant in the context of obesity." (PMID 40710295, 2025). "It has been suggested that in obesity and T2DM the IRS2-mediated insulin signaling is impaired in hepatocytes." (PMID 40572705, 2025). "On the other hand, obesity is a key determinant of both OSA and T2DM, contributing to upper airway collapsibility, insulin resistance, and systemic inflammation." (PMID 40565914, 2025). "These offspring exhibited typical signs of MetS that accompany obesity, including elevated levels of fasting serum TC, TG, FFA, insulin, and leptin, as well as reduced sLepr compared to the control offspring." (PMID 39792613, 2025). "In the 6th week of obesity treatment, glucose tolerance tests (GTT) and insulin tolerance tests (ITT) were performed to assess glucose homeostasis." (PMID 40828622, 2025). "Obesity in mares, manifested by elevated BCS and insulin, had higher concentrations of inflammatory cytokines compared to obese stallions and geldings." (PMID 40901060, 2025). "In interventional studies, mirabegron administration (100 mg/day for four weeks in healthy women, and 50 mg/day in individuals with obesity) led to increases in BAT mass, resting EE, glucose tolerance, and insulin sensitivity." (PMID 40983641, 2025). "Next, we evaluated the importance of p110α in hepatic changes that occur in the pathological context of obesity and MASLD, conditions in which the action of liver insulin is altered." (PMID 40228209, 2025).
Obesity (continued). "Overall, these results suggest a mild improvement in whole‐body insulin sensitivity in Asb2 MKO mice, although the augmented muscle mass was insufficient to counteract HFD‐induced obesity or glucose intolerance." (PMID 40641155, 2025). "SCFAs modulate fat metabolism and insulin sensitivity, and disturbances in SCFA production or absorption can lead to obesity and related metabolic disorders." (PMID 40183584, 2025). "We also looked at the impact of an excessive gestational weight gain on maternal lipid levels and we found that maternal insulin, TG and HOMA–IR were positively correlated with excessive weight gain during pregnancy, particularly among women with obesity." (PMID 40078195, 2025). "Similarly, the preservation of some degree of insulin sensitivity within a subpopulation of adolescent children with obesity is worth additional investigation, and there is increasing recognition that these individuals may be resistant to the adverse metabolic effects of excess adiposity." (PMID 40091831, 2025). "Clinical and metabolic parameters, including insulin, HOMA-IR, leptin, and adiponectin levels, were measured to better describe the obesity profiles of the participants in this study." (PMID 40429924, 2025). "A significantly elevated level of fasting insulin, HOMA-IR, AST, ALT, GGT, TC, TG, LDL-C, ferritin, sUA, and sUA/Cr values was observed in the group of patients with obesity in comparison to the control group (p < 0.001)." (PMID 41298520, 2025). "The criteria included obesity (WC ≥ P90), TGs ≥ P90, HDL-C ≤ 10th percentile [P10], BP (systolic blood pressure [SBP] or diastolic blood pressure [DBP] ≥ P90), and glucose (insulin ≥ P90 or fasting plasma glucose [FPG] ≥ P90)." (PMID 40568560, 2025). "A 14-year-old male with T1D for 6 years, managed with a t:slim insulin pump and decom CGM, also with obesity (BMI 30 kg/m2, weight 84.4 kg) and insulin resistance." (PMID 39707844, 2025). "Obesity correlates with decreased levels of albumin, albumin/globulin ratio, IGF-1, and glucose/insulin ratio." (PMID 40901060, 2025). "While all four groups had comparable rates of hypertension and current smoking, as well as similar levels of obesity, participants who were IGRA+/TST+ and IGRA+/TST- had the highest systolic BP and highest rates of insulin and oral hypoglycemic medication use." (PMID 40315998, 2025). "Post-weaning, 14-week RSV supplementation protected against obesity in pups as HFD total body mass and WAT gain were attenuated, and insulin sensitivity, blood glucose, and lipid profile were improved." (PMID 39598748, 2024). "BMI (33.1 vs. 32.3 kg/m2, p = 0.03), and waist circumference (107 vs. 104 cm, p = 0.02), insulin levels (21 vs. 16.3 μU/mL, p = 0.003), and HOMA-IR (4.6 vs. 3.9, p = 0.02) were higher in HAdV-36-positive subjects with obesity compared to seronegative subjects." (PMID 38932214, 2024). "In the current meta-analysis, indicators related to overweight/obesity and insulin sensitivity include BMI, TG, TC, LDL-C, HDL-C, fasting insulin, HbA1c, and FPG." (PMID 39796489, 2024). "The concentrations of fasting glucose and insulin, the HOMA-IR index, and HbA1C were significantly higher in individuals with obesity than the other two groups at both initial and follow-up assessment." (PMID 39203787, 2024). "In a murine study using Diversity Outbred mice to mimic human obesity, RvE1 treatment after a high-fat diet showed that 50% of the mice were SPM responders, where improvements in gastric inhibitory peptide, insulin, glucagon, and leptin levels were observed." (PMID 39619489, 2024). "In subjects with obesity, FATM, FFM, puberty, age, gender, cholesterol, insulin and creatinine concentrations were identified as significant predictors of FT4 concentrations." (PMID 39203787, 2024).
Obesity (continued). "We reported that the WD induced obesity, glucose intolerance, and NAFLD development, whereas a LCHFD limited weight gain, and maintained a normal glucose regulation, insulin levels and hepatic health, preventing the development of all symptoms." (PMID 38571752, 2024). "Therefore, the improvement in insulin sensitivity could be another potential mediator linking the effects of combined intervention and improvement in executive function in postmenopausal women with obesity." (PMID 38443944, 2024). "According to animal studies, mice without paternally expressed DLK1 exhibit growth retardation and obesity while DLK1 overexpression generate decreased fat mass, diet-induced obesity resistance, and reduced insulin signalling." (PMID 39702541, 2024). "For instance, increased body mass, insulin concentration and higher HOMA-IR in children with obesity were related to higher EF." (PMID 38577274, 2024). "We previously reported that in obesity, HDAC9 expression is increased in the adipose tissues of humans and mice, in conjunction with impaired insulin sensitivity and glucose tolerance." (PMID 38672510, 2024). "Furthermore, notable improvements in insulin sensitivity, along with reductions in markers of inflammation and hepatic steatosis, have been observed, underscoring the therapeutic potential of bergamot extracts in the management of obesity-related metabolic disorders." (PMID 39517207, 2024). "We previously found that BDNF heterozygous mice exhibited hepatic steatosis, one of the most frequent symptoms observed in obesity and that liver lesions of MASH coincide with increased levels of food intake, body weight, serum glucose and insulin." (PMID 38672461, 2024). "In vivo, transgenic miceexpressing porcine TRPC1 (Tg-pTRPC1) on a HFD were used as obesity models to explore the potential effect of TRPC1 on fat deposition, hepatic steatosis, glucose metabolism, and insulin sensitivity." (PMID 39631563, 2024). "Enhancing GLUT4 translocation and the phosphorylation of insulin IRS‐1 and Akt are also therapeutic targets in obesity and diabetic sarcopenia [S21]." (PMID 39385717, 2024). "In people with obesity, elevated levels of FFA released from adipose tissue can inhibit glucose uptake by skeletal muscle cells, which is mediated by insulin." (PMID 38892574, 2024). "Additionally, trodusquemine (MSI‐1436), an investigational drug, has been shown to combat obesity and metabolic disorders by inhibiting the enzyme protein tyrosine phosphatase 1b (Ptp1b), consequently reducing hepatic lipogenesis and counteracting insulin and leptin resistance." (PMID 38798180, 2024). "The regulation of the insulin pathway by RBP4 or AGP, the involvement of A1M in obesity, endoplasmic reticulum stress, and the role of LCN2 and AGP in modulating food intake behavior are only some of the noteworthy features." (PMID 38673873, 2024). "Casein hydrolysates (4%) administered to mice with HFD-induced obesity decreased systemic inflammation induced by the HFD and improved ITT (i.e., IR), reduced fasting insulin and HOMA-IR, although FBG was unchanged compared with the HFD group." (PMID 39272602, 2024). "In this group, there is a higher prevalence of obesity, atrial fibrillation, chronic obstructive pulmonary disease (COPD), chronic kidney disease and an increased use of insulin treatment." (PMID 39597026, 2024). "In conclusion, controlling TRPA1 activation has the potential to combat obesity and T2DM by regulating insulin secretion, GLP-1 release, and insulin sensitivity." (PMID 39273183, 2024). "Pathways related to growth and nutrient utilization (Regulation of eIF4 and p70S6K Signaling, Insulin Secretion Signaling, PPAR Signaling, Leptin Signaling in Obesity) were all inhibited, suggesting cardiac metabolic dysregulation." (PMID 38981849, 2024). "Mice with neuron-specific deletion of PTP-1B exhibit enhanced insulin sensitivity in the hypothalamus and are protected from HFD-induced obesity and related metabolic dysfunctions." (PMID 39684879, 2024).